CD46P1 (CD46 molecule pseudogene 1)
Synonyms: CD46P; MCPL; MCPL1
Gene: Unprocessed pseudogene on chromosome 1 (207,645,234 to 207,657,410, forward strand). Ensembl gene ENSG00000244703.
Diseases named in the same sentence as CD46P1 in open-access papers:
CD46P1 is named in the same sentence as 4 diseases in open-access papers, as found by Europe PMC text mining. Sharing a sentence is not in itself a finding about the gene and the disease.
CD46P1 shares sentences with these, for which no sentence is quoted: Sepsis (2 papers); diabetes mellitus (1); Obesity (1); tumor (1).